WDR62 (WD repeat domain 62)
Diseases named in the same sentence as WDR62 in open-access papers (continued):
Sharing a sentence is not in itself a finding about the gene and the disease.
microcephaly (continued). "WDR62 depletion in NPCs inhibits their self-renewal and induces premature differentiation, which may be related to retarded cilium disassembly, long cilium and delayed cell cycle progression in microcephaly." (PMID 33937237, 2021). "Disruption of oRGs due to WDR62 mutation may lead to the reduction of neurogenesis output specifically in the human cerebral cortex in comparison to that of mice, which could explain drastic organoid size reduction relative to the mild mouse microcephaly upon WDR62 deletion." (PMID 31197141, 2019). "Therefore, the documented and complex effects that WDR62 disruption has on the mitotic cycle of neural progenitors could explain the microcephaly with structural abnormalities in patients with MCPH2." (PMID 28272472, 2017). "A number of microcephaly genes have been identified, including ASPM, microcephalin/BRIT1, CDK5RAP2/Cep215, CENPJ/CPAP, SIL/STIL, WDR62, and NDE1 (refs 3, 4, 5)." (PMID 27553190, 2016). "To determine whether estradiol could regulate the seven currently known microcephaly genes (ASPM, CENPJ, CEP152, CDK5RAP2, MCPH1, STIL and WDR62), we conducted a search of the potential ERE (estrogen response element) sites in gene promoter regions." (PMID 26123139, 2015). "Comparisons of the gene-wide average dN/dS between primates and non-primate mammals are significant for all microcephaly loci except WDR62." (PMID 24898820, 2014). "Notably, distinct CHD phenotypes were observed in Wdr62‐null mice and the heart defects, rather than microcephaly, were the only deformities of which the ratio was significantly increased in HE mice compared with WT." (PMID 35808830, 2022). "This is not surprising as several of the key primary microcephaly genes (CDK5RAP2, ASPM, WDR62, and MCPH1) are essential for the control of mitosis and cell cycle progression." (PMID 36845425, 2023).
Primary microcephaly (22 papers, 2011 to 2026). Head circumference below 2 standard deviations below the mean for age and gender at birth. "Inherited mutations in the spindle pole-associated scaffold protein WDR62 cause autosomal recessive primary microcephaly." (PMID 41787126, 2026). "Variants in WDR62 have been associated with primary microcephaly, intellectual disability, and cerebral hypoplasia." (PMID 41555927, 2025). "WDR62 is the second most frequently mutated gene associated with primary microcephaly in the Pakistani population, with most reported variants being missense substitutions." (PMID 41555927, 2025). "Due to the atypical clinical picture, the diagnosis of primary microcephaly associated with mutations in the WDR62 gene is possible only with the use of whole-exome sequencing or a panel of selected genes." (PMID 33921653, 2021). "WDR62 is one of the most commonly mutated autosomal recessive primary microcephaly-associated genes, with over 30 identified mutations leading to reduced brain size and a spectrum of cortical abnormalities." (PMID 34326322, 2021). "Wdr62 is implicated in primary microcephaly, and both Cnb and Wdr62 are necessary for MTOC asymmetry by regulating Polo’s and Plp’s centrosomal localization in interphase neuroblasts." (PMID 32760088, 2020). "Primary microcephaly is caused by mutations in genes encoding centrosomal proteins including WDR62 and KIF2A." (PMID 31197141, 2019). "Mutations in WD40-repeat protein 62 (WDR62) are commonly associated with primary microcephaly and other developmental cortical malformations." (PMID 28690640, 2017). "In present work, we report identification of a novel and three known mutation in WDR62 gene in four additional Pakistani families with autosomal recessive primary microcephaly." (PMID 21961505, 2011). "Our data indicate that WDR62 mutations cause about 4% of autosomal recessive primary microcephaly in Pakistan." (PMID 21961505, 2011). "Mutations in WDR62 can cause primary microcephaly and premature ovarian insufficiency." (PMID 34059773, 2021). "WD repeat domain 62 genes (WDR62 – GenBank Accession NM_005682.5) are known to play important role in cerebral cortical development and any mutations in this gene lead to cortical malformations, mental retardation and primary microcephaly." (PMID 31258591, 2019). "However, Most of the mutations have been reported in two abnormal spindle microtubule assembly (ASPM) OMIM 608716 genes accounting for more than half of all mutations; and WDR62 gene around 10% of all reported cases related to primary microcephaly." (PMID 31258591, 2019). "Exome sequencing followed by Sanger sequencing in a German family with two affected daughters with primary microcephaly revealed in the index patient the compound heterozygous mutations c.1313G>A (p.R438H) / c.2864-2867delACAG (p.D955Afs*112) of WDR62, the second of which is novel." (PMID 24228726, 2013). "Genes associated with primary microcephaly were often differentially expressed during development, with highest expression during the early embryonic and fetal periods (ASPM, WDR62, MCPH1, STIL, KIF23 and TTI1)." (PMID 32182809, 2020). "Primary microcephaly (MCPH) associated proteins CDK5RAP2, CEP152, WDR62 and CEP63 colocalize at the centrosome." (PMID 26297806, 2015). "Our study identifies regulatory functions of WDR62 in purine metabolism that may contribute to primary microcephaly." (PMID 41787126, 2026). "Mutations in WDR62 were reported to cause primary microcephaly with or without severe brain malformations (lissencephaly and pachygyria)." (PMID 34068194, 2021). "However, the high frequency of WDR62 mutations in consanguineous primary microcephaly patients will especially simplify the clinical counseling and diagnostic screening of non-consanguineous primary microcephaly patients." (PMID 25303973, 2014).
Primary microcephaly (continued). "We report a novel compound heterozygous mutations c.797C>T in exon 7 and c.1102G>A in exon 9 of the WD repeat domain 62 (WDR62) (OMIM 604317) gene in two affected siblings in Saudi family with intellectual disability, speech impediments walking difficulty along with primary microcephaly." (PMID 31258591, 2019). "By and large, primary microcephaly patients are phenotypically indistinguishable, however, recent studies in patients with mutations in MCPH1, WDR62 and ASPM genes showed a broader clinical and/or cellular phenotype." (PMID 21668957, 2011).
autosomal recessive primary microcephaly (11 papers, 2013 to 2025). Autosomal recessive primary microcephaly (MCPH) is a rare genetically heterogeneous disorder of neurogenic brain development characterized by reduced head circumference at birth with no gross anomalies of brain architecture and variable degrees of intellectual impairment. "Recessive mutations in WDR62 cause structural brain abnormalities and account for the second most common cause of autosomal recessive primary microcephaly (MCPH), indicating WDR62 as a critical hub for human brain development." (PMID 37272619, 2023). "Mutations in WDR62 are known to be the second most common cause of autosome recessive primary microcephaly (MCPH) after ASPM." (PMID 33937237, 2021). "WD40-repeat protein 62 (WDR62) mutations are common genetic causes of human autosomal recessive primary microcephaly (MCPH), a neurodevelopmental disorder characterized by significantly reduced cerebral cortex size at birth." (PMID 28690640, 2017). "Both approaches prioritized the same homozygous novel frameshift mutation (p.Arg608Serfs*26) in WDR62, a gene known to cause autosomal recessive primary microcephaly." (PMID 24479948, 2014). "Mutations of WD repeat domain 62 (WDR62) lead to autosomal recessive primary microcephaly (MCPH), and down-regulation of WDR62 expression causes the loss of neural progenitor cells (NPCs)." (PMID 30566428, 2018). "WD repeat domain 62 (WDR62) was identified as the second most common gene for autosomal recessive primary microcephaly (MCPH) in human." (PMID 30566428, 2018). "Mutations in a number of identified genes have been found to underlie autosomal recessive primary microcephaly (MCPH) (e.g., MCPH1, ASPM, CASC5, and WDR62) and thanatophoric dysplasia (FGFR3), a subtype of megalencephaly." (PMID 31338027, 2019). "Autosomal Recessive Primary Microcephaly (MCPH) is one of those, for which seven loci (MCPH1-MCPH7) with the corresponding genes (MCPH1, WDR62, CDK5RAP2, CEP152, ASPM, CENPJ, and STIL) have been reported so far." (PMID 24148351, 2013).
gastric cancer (6 papers, 2020 to 2025). A primary or metastatic malignant neoplasm involving the stomach. "What is more, overexpression of WDR62 is associated with poor prognosis in lung adenocarcinoma and gastric cancer." (PMID 32370292, 2020). "Similarly, WDR62 expression is significantly increased in gastric cancer tissues and cell lines, and it is associated with poor differentiation and prognosis as well as multidrug resistance in gastric cancer." (PMID 33937237, 2021). "WDR62 also contributes to multidrug resistance of gastric cancer through activation of MAPK signaling." (PMID 40585306, 2025). "Knockdown of WDR62 significantly decreased gastric cancer cell proliferation and induced G2/M phase arrest of gastric cancer cells." (PMID 40369663, 2025). "In addition, WDR62 can also lead to multidrug resistance in gastric cancer and oxaliplatin resistance in colorectal cancer through the activation of MAPK signaling." (PMID 40369663, 2025). "WDR62 expression was significantly elevated in gastric cancer tissues and cell lines." (PMID 40369663, 2025). "Moreover, we simultaneously down-regulated KPNA2 (sh-1 or sh-2) and up-regulated WDR62 in gastric cancer cells, and found that overexpression of WDR62 reversed the KPNA2 knockdown-induced inhibition of proliferation, migration and invasion." (PMID 39060340, 2024). "In addition, knockdown of WDR62 reversed the resistance in gastric cancer cells to 5-FU, cis-diaminodichloroplatinum (CDDP), and adriamycin (ADM), and elevated expression of WDR62 led to resistance to oxaliplatin and cetuximab in colorectal cancer patients." (PMID 40369663, 2025).
Lissencephaly (5 papers, 2015 to 2026). A spectrum of malformations of cortical development caused by insufficient neuronal migration that subsumes the terms agyria, pachygyria and subcortical band heterotopia. "Mutation of WDR62, for example, also results in a variety of structural brain disorders including lissencephaly, cerebellar hypoplasia and hypoplasia of the corpus callosum." (PMID 28334956, 2017). "Cortical disruptions that derive from mutations in genes such as NDE1, LIS1, PP4c, WDR62, CENPE, TCOF1, AGS3, VANGL2 and HTT, are classified as micro- or macro-cephaly, and/or cortical disorganization and abnormal cortical architecture, lissencephaly and simplified gyral patterns." (PMID 25729350, 2015).
lung adenocarcinoma (5 papers, 2020 to 2025). A carcinoma that arises from the lung and is characterized by the presence of malignant glandular epithelial cells. "WDR62 mRNA level is significantly overexpressed in lung adenocarcinoma and a multivariate analysis revealed that WDR62 overexpression is an independent predictor of a poor survival outcome among lung adenocarcinoma patients." (PMID 33937237, 2021). "The top three genes (WDR62, CDT1 and MCM2) positively correlated with POLD1 expression play important roles in cell proliferation and apoptosis, and their upregulation has been proved to be associated with tumors development and worse prognosis, such as breast cancer and lung adenocarcinoma." (PMID 35189839, 2022).
prostate carcinoma (5 papers, 2021 to 2025). A carcinoma that arises from epithelial cells of the prostate gland. "We observed that the knockdown of WDR62 results in loss of TPX2 and AURKA protein suggesting WDR62 regulates the stability of this protein complex in prostate cancer cells." (PMID 34326322, 2021). "Our data demonstrated KIF4A and WDR62 are AR-independent prostate cancer driver genes that are associated with poor prognosis in patients with advanced metastatic disease." (PMID 34326322, 2021). "Two highlighted hits, KIF4A and WDR62, reported to influence prostate carcinoma survival and aggressive behavior, were also identified in our LNCaP_FGC screen." (PMID 40956611, 2025). "Knockdown of WDR62 also inhibited the migration and invasion of prostate cancer cells, while WDR62 overexpression increased migration and invasion." (PMID 40369663, 2025). "Together, these data suggest that WDR62 is a prostate cancer-specific driver gene and in addition is a potential therapeutic target in mCRPC." (PMID 34326322, 2021). "The identification of WDR62 and additional hit genes as poorly characterized prostate cancer driver genes highlights the strength of our integrated clinical and functional genomics analysis strategy." (PMID 34326322, 2021). "We demonstrated that two of these genes, KIF4A (Kinesin Family Member 4A) and WDR62 (WD Repeat Domain 62), promote aggressive prostate cancer phenotypes in vitro and in vivo." (PMID 34326322, 2021). "Our functional genomics filters nominated WDR62 as being selectively essential in prostate cancer models." (PMID 34326322, 2021). "Genetically engineered mouse models of prostate cancer are needed to further explore the biology of how WDR62 promotes tumorigenesis, metastasis, and drug response." (PMID 34326322, 2021). "Here, the authors perform genome-wide CRISPRi screens and integrate these data with metastatic prostate cancer functional and clinical genomics data to show that KIF4A and WDR62 drive aggressive prostate cancer phenotypes." (PMID 34326322, 2021). "We were intrigued by the observation that WDR62 is an uncharacterized top CRISPRi screen hit gene that is crucial for prostate cancer cell proliferation or survival." (PMID 34326322, 2021). "We also observed that knockdown of WDR62 suppressed the ability of prostate cancer cells to migrate/invade, while WDR62 overexpression increased migration and invasion." (PMID 34326322, 2021). "These experiments, combined with clinical data on these genes, serve to nominate KIF4A and WDR62 as prostate cancer-specific driver genes." (PMID 34326322, 2021). "However, to experimentally confirm this, we repressed WDR62 expression in our panel of diverse CRISPRi non-prostate cancer cell-line models." (PMID 34326322, 2021). "A top hit in our CRISPRi screen is WDR62, an uncharacterized gene in prostate cancer." (PMID 34326322, 2021). "We hypothesized that WDR62 may regulate the stability or function of the TPX2/AURKA protein complex in prostate cancer cells." (PMID 34326322, 2021). "Basal protein expression of WDR62 was similar across this panel of non-prostate cancer cell lines." (PMID 34326322, 2021). "Additional top hits, such as WDR62, are uncharacterized in prostate cancer." (PMID 34326322, 2021). "Collectively, these data suggest that WDR62 is selectively essential in prostate cancer models." (PMID 34326322, 2021). "In clinical genomics data, we observed that the expression of WDR62 is significantly higher in primary (TCGA) and metastatic (MSKCC) prostate cancer samples relative to benign prostate samples." (PMID 34326322, 2021). "This experiment demonstrated that WDR62 interacts with TPX2 and AURKA likely forming a protein complex in prostate cancer cells." (PMID 34326322, 2021). "To further confirm that WDR62 is a prostate cancer-specific regulator of the TPX2/AURKA protein complex, we examined WDR62, AURKA, TPX2 genetic dependencies in the DepMap." (PMID 34326322, 2021).
prostate carcinoma (continued). "We demonstrated both in vitro and in vivo that WDR62 promotes aggressive prostate cancer phenotypes in all of the prostate cancer models that were tested, irrespective of AR-status, suggesting that this is an AR-independent human prostate cancer driver gene." (PMID 34326322, 2021). "Overexpression of WDR62 significantly increased clonogenic survival of both malignant and benign prostate cells suggesting WDR62 is a driver gene in prostate cancer that is likely independent of AR." (PMID 34326322, 2021). "In order to demonstrate that the hits identified by these two integrated functional and clinical genomics approaches are potential prostate cancer-specific driver genes, we chose to study KIF4A and WDR62 as they were relatively uncharacterized in the context of mCRPC." (PMID 34326322, 2021). "KIF4A and WDR62 drive aggressive prostate cancer phenotypes irrespective of AR-status." (PMID 34884583, 2021). "Notably, only a single prostate cancer cell line (VCaP) is represented in the DepMap data and so we do not expect a pan-cancer correlation between TPX2 and WDR62 if the biology of WDR62 is prostate cancer-specific." (PMID 34326322, 2021).
brain malformations (4 papers, 2011 to 2021). "Recessive WDR62 mutations were identified in severe brain malformations, and the interaction between WDR62 and mitotic kinase AURKA is essential for drosophila brain growth." (PMID 32370292, 2020). "Cerebral cortical development, proliferation and migration of neuronal precursors, mutation in WDR62 affects its role in proliferating and migrating neural precursors and causes severe brain malformations." (PMID 25951892, 2015). "Phenotypic variations of WDR62 advocate its key role in numerous aspects of cerebral cortical development; it has been linked with severe brain malformations." (PMID 25951892, 2015).
Infertility (4 papers, 2021 to 2023). "Mutations or deficiency of WDR62 causes many diseases in humans, such as neurological disorders, infertility, and tumorigenesis." (PMID 36571716, 2023). "The Wdr62-KO mice showed a normal lifespan but infertility, similar to gene trap mice reported previously." (PMID 36571716, 2023). "The WD40-repeat protein 62 (WDR62) is a scaffold protein that recruits different components of the JNK signaling pathway to regulate several human diseases including neurological disorders, infertility, and tumorigenesis." (PMID 33937237, 2021).
bladder cancer (3 papers, 2021 to 2025). "Knockdown of WDR62 significantly inhibited the proliferation, migration, and invasion of bladder cancer cells and induced apoptosis." (PMID 40369663, 2025). "Recently, accumulating evidence suggests that WDR62 is a new identified tumor biomarker in few tumors such as lung cancer and bladder cancer." (PMID 34306258, 2021).
developmental delays (3 papers, 2019 to 2023). "We examined developmental and behavioral phenotypes in different lines of Wdr62-KO mice, which have global developmental delays with impaired cognitive and social interaction functions." (PMID 36571716, 2023).